RNU6-1053P (RNA, U6 small nuclear 1053, pseudogene)
Gene: Small nuclear RNA gene on chromosome 4 (183,705,931 to 183,706,031, forward strand). Ensembl gene ENSG00000251739.
Homologues: Orthologues: chimpanzee U6 (100% identical), macaque U6 (83% identical), guinea pig U6 (80% identical), mouse Gm26164 (78% identical), pig U6 (78% identical), dog U6 (77% identical). Paralogues in human: RNU6-1060P (84% identical), RNU6-672P (83% identical), RNU6-949P (83% identical), RNU6-19P (82% identical), RNU6-266P (82% identical), RNU6-1011P (81% identical), RNU6-1117P (81% identical), RNU6-1152P (81% identical), RNU6-116P (81% identical), RNU6-12P (81% identical), RNU6-1303P (81% identical), RNU6-13P (81% identical), and 1290 more.